ERCC1 (ERCC excision repair 1, endonuclease non-catalytic subunit)
Diseases named in the same sentence as ERCC1 in open-access papers (continued):
Sharing a sentence is not in itself a finding about the gene and the disease.
seminoma (5 papers, 2016 to 2022). A radiosensitive malignant germ cell tumor found in the testis (especially undescended), and extragonadal sites (anterior mediastinum and pineal gland). "Furthermore, non seminomas primary tumors, who generally exhibit a higher resistance to chemotherapy, show a higher ERCC1 (excision Repair Cross Complementation group 1) protein expression compared with seminoma tissues." (PMID 29416701, 2018). "The expression levels of all three NER proteins were higher in non-seminomas compared to seminomas, although for ERCC1 the difference was not statistically significant." (PMID 31906898, 2020). "In the case of GCTs, non-seminomas display higher expression levels of the ERCC1 repair factor compared to seminomas and normal testicular tissue." (PMID 27732956, 2016). "In addition, the expression of ERCC1 and XPF proteins was shown to be higher in non-seminomas compared to seminomas and normal testis tissue." (PMID 35625709, 2022).
testis tumor (5 papers, 2006 to 2024). "Therefore, the repair complex ERCC1-XPF appears to be responsible at DNA level for the exquisite cisplatin sensitivity of testis tumors." (PMID 20846399, 2010). "This is consistent with reports that have shown significantly lower levels of ERCC1, XPF, and XPA protein in testis tumor cell lines do not cohere with the transcriptional efficiency or mRNA stability of the cognate factors." (PMID 21385444, 2011).
glomerulosclerosis (4 papers, 2020 to 2025). A hardening of the kidney glomerulus caused by scarring of the blood vessels. "This cascade could be modulated through well-timed mTORC1 inhibition as suggested by the ameliorated SNP expression, increased SD length, and reduction of glomerulosclerosis in rapamycin-treated Ercc1-deficient animals." (PMID 40392611, 2025). "At week 13, Ercc1-pko mice developed severe generalized renal damage, including glomerulosclerosis, interstitial fibrosis, and tubular atrophy with protein casts." (PMID 40392611, 2025). "Restoration of podocyte ERCC1 expression attenuated proteinuria and glomerulosclerosis with reduced DNA damage." (PMID 38773208, 2024). "We then focused our attention on the kidney phenotype, as Ercc1-/- mice show abnormal renal histopathology (glomerulosclerosis and protein casts) and renal dysfunction (significantly elevated serum creatinine and urea)." (PMID 32271760, 2020). "Similarly, Ercc1-/Δ7 mice show glomerulosclerosis and tubular atrophy, consistent with accelerated renal aging." (PMID 40684071, 2025). "We hypothesize this to result from the retained ability of successful DNA damage repair through Ercc1 in aged WT mice, contributing to the milder phenotype without pronounced glomerulosclerosis compared with the Ercc1-pko mice." (PMID 40392611, 2025).
laryngeal carcinoma (4 papers, 2014 to 2019). Carcinoma that arises from the laryngeal epithelium. "Polymorphisms in other NER genes including ERCC1, ERCC2, ERCC3, ERCC4, ERCC5, and XPA have also been reported to pose as an increased risk in Laryngeal Cancer." (PMID 30410671, 2018). "Beginning with DNA repair genes, less common genotypes in ERCC1 rs11615 (p = 0.011, OR = 0.288 (CI 95% = 0.110–0.751) in a recessive model) and ERCC2 rs13181 (p = 0.046, OR = 0.375 (0.143–0.982) in a codominant model) were associated with a lower risk of laryngeal cancer." (PMID 30959967, 2019). "Similarly, Johung and coauthors published that ERCC1 expression did not predict radiotherapy resistance in laryngeal cancer." (PMID 24817012, 2014).
liver cancer (4 papers, 2014 to 2024). An epithelial or non-epithelial malignant neoplasm that arises from the liver. "Only two other studies from this province have involved examination of ERCC1 polymorphisms and cancer, however these were focused on colorectal and liver cancer." (PMID 25191856, 2014). "Our results in yeast were further corroborated upon analysis of whole exome sequenced liver cancers, wherein, tumors with defects in ERCC1 and ERCC4 (NER), FANCD2 (ICL repair) or SPRTN (DPC repair) carried a higher gCn→A mutation load than tumors with no deleterious mutations in these genes." (PMID 38260495, 2024). "Interestingly, a study in liver cancer model showed that tumor cells that failed at H3K9Ac/H3K9Me3 transition, could lead to the hyperacetylation of H3K9 and increased expression of many oncogenes such as Kras, Ercc1, Cdk6, Usp39, and Mapre352." (PMID 36064736, 2022).
metastatic colorectal cancer (4 papers, 2009 to 2015). "Overall, these findings suggest that measurement of ERCC1 and TS expression has potential clinical utility in managing patients with metastatic colorectal cancer." (PMID 26083491, 2015).
adenoma (3 papers, 2006 to 2014). A neoplasm arising from the epithelium. "We used a case-control study design (156 carcinomas, 981 adenomas and 399 controls) to test the association between polymorphisms in the chromosomal region 19q13.2-3, encompassing the genes ERCC1, ASE-1 and RAI, and risk of colorectal adenomas and carcinomas in a Norwegian cohort." (PMID 16817948, 2006). "Other studies showed that mRNA levels of OGG1 and ERCC1 genes are significantly increased in colon lesions in the adenoma-carcinoma pathway, and that this increase was higher in severe lesions, namely severe adenomas and carcinomas, than in mild ones." (PMID 25526641, 2014). "We have examined mRNA expression of two DNA repair genes, ERCC1 and OGG1 as well as the putative apoptosis controlling gene RAI, in normal tissues and lesions from 36 cases with adenomas (mild/moderat n = 21 and severe n = 15, dysplasia) and 9 with carcinomas." (PMID 16914027, 2006). "For all three genes, ERCC1, OGG1 and RAI, a comparison of expression levels between normal colonic mucosa and lesions in all cases combined (adenomas and CRC) yielded significantly higher expression levels in lesions, 3.3-fold P = 0.005, 5.6-fold P < 3*10-5 and 7.7-fold P = 0.0005, respectively." (PMID 16914027, 2006).
Ataxia (3 papers, 2012 to 2023). Ataxia refers to impaired coordination of voluntary muscle movement. "First, while Ercc1 Δ/- mice have accelerated multiorgan degenerative changes, the proximate cause of death is likely neurologic, as ataxia and incoordination are early and prominent features, and loss of Purkinje neurons are a manifestation of Ercc1 Δ/- pathology." (PMID 37220109, 2023).
breast tumors (3 papers, 2015 to 2021). "On the other hand, it has been reported that the mortality rate was significantly reduced in patients receiving cisplatin-based chemotherapy with negative-ERCC1 non-small cell lung and breast tumors compared to ERCC1- positive tumors." (PMID 34680470, 2021). "Using median as the cut off (H-score ≥ 130), we observed ERCC1 nuclear protein expression in 439/991 (44.3%) of breast tumours, and 55.7% (552/991) were negative for ERCC1 expression." (PMID 31405143, 2019). "Finally, as pCR is rarely achieved by NCT in ER+ breast tumors, we searched if BRCA1 (Pro871Leu), ERCC1 (Asn118Asn), CYP1B1 (Leu432Val) and SLCO1B3 (IVS12-5676) could stand for predictive markers of NCT for patients with this subtype of tumor." (PMID 26180747, 2015).
cardiac failure (3 papers, 2023 to 2024). "Our findings with Ercc1 deficiency are also consistent with a prior study demonstrating that deletion of Xrcc1, essential for repair of spontaneous, endogenous DNA singlestrand breaks, exacerbates heart failure in a mouse model of pressure overload‐induced heart failure." (PMID 36734200, 2023). "Overexpression of mitCAT in Ckmm‐Cre+/−;Ercc1−/fl mice attenuated expression of heart failure markers Anp and Bnp consistent with increased ROS contributing to disease pathogenesis." (PMID 36734200, 2023). "In this study, we explored the role of apoptosis as a potential biomarker for cardiac failure using functional micro-CT and fluorescence molecular tomography (FMT) imaging techniques in Ercc1 mutant mice." (PMID 38498063, 2024). "Since Xpg and Ercc1 are both involved in NER, TCR and pathways of DSB repair, these genome stability mechanisms protect against cardiac failure." (PMID 36756698, 2023).
cognitive decline (3 papers, 2012 to 2022). "Further, mice carrying a neuron specific mutation in Ercc1 (excision repair cross-complementing group 1, knockout), have impaired DNA repair, including of DSBs, and show both DNA damage and neurodegeneration, and age-dependent cognitive decline and by 6-months." (PMID 29618789, 2018). "Given that our AUD subjects showed significantly reduced Ercc1 expression and performance on several standardized measures of verbal function, the present study strongly suggests a role for DNA repair processes and Ercc1 in preventing alcohol-dependent cognitive decline as well." (PMID 23095216, 2012).
colon adenocarcinoma (3 papers, 2012 to 2022). "When absorptive cells of a crypt near a colonic adenocarcinoma are deficient in expression of Pms2, Ercc1 or Xpf, they are also often similarly deficient in all of the crypts within the tissue section." (PMID 22494821, 2012). "In both colon adenocarcinoma (fold change = 3.075, P = 1.67E − 13) and rectal adenocarcinoma (fold change = 3.813, P = 1.79E − 16), ERCC1 was consistently upregulated in cancer tissues." (PMID 29568775, 2018).
colorectal tumors (3 papers, 2014 to 2023). "As our results indicated, about 55% of colorectal tumors showed methylation of ERCC1-promoter region, which is significantly higher than normal adjacent control." (PMID 37510370, 2023). "The present study determines the specificity of a novel antibody, monoclonal antibody 4F9, and presents a method to evaluate ERCC1 expression in colorectal tumor specimens." (PMID 24603753, 2014). "The current studies indicate that the resistance mechanisms of colorectal tumors to L-OHP may be related to the miRNA mediated regulation of ERCC1, but no in-depth studies on the miRNAs that affect drug resistance and ERCC1 gene expression have been performed." (PMID 33014113, 2020). "The resistance mechanism(s) of colorectal tumors to L-OHP may be related to the regulation of ERCC1 by cancer-expressed miRNAs, but no in-depth studies on the miRNAs that affect drug resistance have been performed." (PMID 33014113, 2020).
coronary artery disease (3 papers, 2017 to 2023). "There is at least one single nucleotide polymorphism in ERCC1 significantly associated with coronary artery disease." (PMID 36734200, 2023).
esophageal adenocarcinoma (3 papers, 2014 to 2022). A malignant tumor with glandular differentiation arising predominantly from Barrett mucosa in the lower third of the esophagus. "Additionally, variant alleles in NER SNPs ERCC2 Lys751Gln, ERCC1 8092 C/A and ERCC1 118C/T were individually associated with esophageal adenocarcinoma risk." (PMID 35955506, 2022). "Upon review of the literature, many recent studies investigating polymorphic variations in ERCC1 and the predictive potential for patient and platinum-based treatment effects take place in Europe or the United States where ESCC is far less common than esophageal adenocarcinoma." (PMID 25191856, 2014).
gastric tumors (3 papers, 2013 to 2020). "Increased expression of the NER gene ERCC1 (RAD10 in budding yeast) is frequently associated with CP resistance in ovarian and gastric tumors." (PMID 24130896, 2013). "PPI and EVO both could inhibit the activity of freshly-removed gastric tumor, and they could enhance the anticancer effect of Pt and 5-FU by reducing the mRNA expression levels of ERCC1 and TS." (PMID 23762305, 2013). "Moreover, the mechanism of PPI and EVO enhancement of the anticancer effect of Pt and 5-FU in gastric tumor might be due to their ability of reduce the mRNA expression levels of ERCC1 and TS." (PMID 23762305, 2013). "To explore whether Pt, 5-FU and CPT-11 associated gene is involved in the anticancer effects of PPI and EVO on the freshly-removed gastric tumors, we first examined the mRNA expression levels of ERCC1, TS, TOPO1 and APTX in the samples before any drugs administration." (PMID 23762305, 2013). "After incubation with PPI (200 μg/ml) or EVO (200 μg/ml) for 3days, mRNA expression levels of ERCC1, TS, TOPO1, and APTX in freshly-removed gastric tumors were assessed by quantitative RT-PCR." (PMID 23762305, 2013).
Infertility (3 papers, 2007 to 2024). "Another hallmark of ERCC1 deficiency is infertility and germ cell failure." (PMID 38514641, 2024).
neuropathy (3 papers, 2015 to 2020). A disorder affecting the nervous system that manifests with pain, tingling, numbness, and/or muscle weakness. "ABCC2 and GSTP1 were associated with both platinum- and taxane-induced neuropathy; CYP2C8 was associated with both taxane- and platinum/taxane-induced neuropathy; and ERCC1 was associated with platinum- and platinum/taxane-induced neuropathy." (PMID 26269716, 2015). "A Japanese study of colorectal cancer patients treated with oxaliplatin‐based chemotherapy estimated the pharmacogenetic correlation between neuropathy and polymorphisms of the excision repair cross‐complementation Group 1 (ERCC1) and glutathione‐S‐transferases pi 1 (GSTP1) genes." (PMID 28127506, 2017). "The study revealed that polymorphisms of ERCC1, C118T, and GSTP1 Ile105Val made patients more susceptible to oxaliplatin‐induced neuropathy." (PMID 28127506, 2017).
Oral Squamous Cell Carcinoma (3 papers, 2019 to 2023). "The aim of this study was to investigate the expression of the excision repair cross-complementation group 1 (ERCC1) in oral squamous cell carcinoma (OSCC) and the possible association of ERCC1 polymorphisms with susceptibility and response to chemotherapy of OSCC in a Chinese Han population." (PMID 33029487, 2020).
osteoporosis (3 papers, 2021 to 2024). A condition of reduced bone mass, with decreased cortical thickness and a decrease in the number and size of the trabeculae of cancellous bone (but normal chemical composition), resulting in increased fracture incidence. "Genetic mutations in the ERCC1-XPF gene in humans have been shown to have progeria like state with osteoporosis as one of the phenotypic pathologies." (PMID 33805567, 2021). "The Ercc1-/Δ mice develop many age-related diseases including severe and progressive osteoporosis, premature senescence of osteoblastic progenitors and enhanced osteoclastogenesis." (PMID 38352710, 2024). "Ercc1-null and hypomorphic mice both displayed severe osteoporosis, with bone resorption outpacing bone formation." (PMID 33805567, 2021). "This study demonstrated that the combination of dasatinib and quercetin effectively eliminated senescent mouse embryonic fibroblasts, and that periodic drug administration extended healthspan in Ercc1 knock-out mice, thereby delaying age-related symptoms and pathologies, including osteoporosis." (PMID 39267978, 2024).
ovarian tumor (3 papers, 2013 to 2017). "ERCC1 has been associated with cisplatin resistance in ovarian tumors and cancer cell lines." (PMID 23537295, 2013). "We have previously demonstrated that cisplatin exposure activates an AP-1-mediated increase in ERCC-1 expression in human ovarian tumor cells." (PMID 23817665, 2013). "In summary, this meta-analysis suggests that the C19007T polymorphism of the ERCC1 does not contribute to the platinum-based chemotherapy effectiveness in ovarian tumor." (PMID 28623887, 2017). "In the current study, β-elemene promoted cisplatin cytotoxicity and apoptosis by blocking cisplatin-induced increases in the levels of ERCC-1 and XIAP in resistant ovarian tumor cells." (PMID 23817665, 2013).
Thrombocytopenia (3 papers, 2011 to 2024). A reduction in the number of circulating thrombocytes. "We found that ERCC1 was significantly associated with PFS and ERCC2 with thrombocytopenia." (PMID 39339159, 2024).
xeroderma pigmentosum group A (3 papers, 2009 to 2024). Any xeroderma pigmentosum in which the cause of the disease is a mutation in the XPA gene. "The expression of ERCC1-XPF (excision repair cross-complementation group 1-xeroderma pigmentosum group F) DNA repair endonuclease is reduced to ~5% compared with Ercc1+/+ mice." (PMID 27774093, 2016).
basal cell carcinoma (2 papers, 2008 to 2013). A carcinoma involving the basal cells. "The polymorphisms in ERCC1 and in particular RAI are strongly associated with risk of basal cell carcinoma." (PMID 18289367, 2008).
biliary tract cancer (2 papers, 2010 to 2019). "This study aims to compare the clinico-pathological characteristics and prognostic factors of GB and bile duct cancers, and also investigate the expression and clinical significance of TP and ERCC1, including several cell-cycle regulatory proteins in biliary tract cancers." (PMID 20955617, 2010). "Various reports have shown the inverse correlation between high ERCC1 expression levels and clinical CDDP efficacy in patients with ovarian, lung, nasopharyngeal, esophageal, cervical, head and neck, and biliary tract cancer." (PMID 31450627, 2019).
cervical adenocarcinoma (2 papers, 2012 to 2022). An adenocarcinoma arising from the cervical epithelium. "The results turned out that a positive association between ERCC1 expression and sensitivity to cisplatin in cervical adenocarcinoma cells (HCA-1 and TCO-2)." (PMID 36713431, 2022). "From the point of view of ERCC1 suppression, such combination therapy with cisplatin and 5-FU might be a promising treatment regimen for cervical adenocarcinoma." (PMID 36713431, 2022). "Thus, co-administration of cisplatin and 5-FU showed synergistic or additive effects via inhibiting of ERCC1 expression, indicating a clinical advantage of combining these two drugs for suppressing ERCC1 in cervical adenocarcinoma cells." (PMID 36713431, 2022).
cervical tumors (2 papers, 2017 to 2022). "According to this study, it might be possible to identify cervical tumors likely to be resistant to cisplatin by examining pre-treatment ERCC1 mRNA levels." (PMID 36713431, 2022).
chronic kidney disease (2 papers, 2013 to 2025). Impairment of the renal function secondary to chronic kidney damage persisting for three or more months. "In Ercc1 knockout animals rescued for their severe lifespan-limiting, aging-related liver pathology, proteinuria and progressive chronic kidney disease are suggestive of a role of Ercc1 in glomerular cell biology." (PMID 23947592, 2013).
colorectal adenoma (2 papers, 2006). An adenoma that arises from the colon or rectum. "In this study we have measured mRNA levels of ERCC1, OGG1 and RAI in patients with colorectal adenomas and carcinomas (normal colonic mucosa and lesions)." (PMID 16914027, 2006). "In conclusion, mRNA levels of ERCC1 and OGG1 were up-regulated in both colorectal adenomas and carcinomas compared to corresponding normal colonic mucosa, indicating that increased expression of defense genes is an early event in the progression of colorectal adenomas to CRC." (PMID 16914027, 2006).